BCL2 (BCL2 apoptosis regulator)
Diseases named in the same sentence as BCL2 in open-access papers (continued):
Sharing a sentence is not in itself a finding about the gene and the disease.
epilepsy (28 papers, 2011 to 2025). A brain disorder characterized by episodes of abnormally increased neuronal discharge resulting in transient episodes of sensory or motor neurological dysfunction, or psychic dysfunction. "BCL2 has been associated with a neuroprotective property in relation to epilepsy." (PMID 39767775, 2024). "We found that PTZ-induced epilepsy in mice was associated with increased cytosolic cytochrome c contents and pro-apoptotic protein expression (Bax and caspase-3), in addition to a decrease in anti-apoptotic protein expression (Bcl-2)." (PMID 35336729, 2022). "Quantitative real-time PCR (qRT-PCR) was performed to assess Klotho and epilepsy-associated gene expression (STAT3, Bax, Bcl2)." (PMID 40351444, 2025). "One important aspect of the pathophysiology of epilepsy is apoptosis, or programmed cell death, which is largely regulated by important proteins including Bcl-2 and Bax." (PMID 40540445, 2025). "Our findings suggest that epilepsy results in a 66% decrease in BCL2 gene expression and a 3.34‐fold increase in BAX gene expression relative to the control group." (PMID 41523603, 2025). "The results showed that CUR protected the animals against epilepsy through the activation of the B-cell lymphoma 2 (Bcl-2) family progenitors and the P38 MAPK pathways." (PMID 36678859, 2023). "In the current study, (-) pseudosemiglabrin increased Bcl-2 level, PI3K, and Akt mRNA expression while decreasing Bax, caspase-3, and the Bax/Bcl-2 ratio in a mouse model of pilocarpine-induced epilepsy." (PMID 37445950, 2023). "The epilepsy group displayed a significantly increased ratio of Bcl-2/Bax (p < 0.05) and decreased expression of the apoptosis-related protein cleaved caspase-3, compared to the control group (p < 0.05)." (PMID 36064418, 2022). "Bcl-2 upregulation in refractory epilepsy neurons significantly decreased cell apoptosis to 60.0% ± 7.1% (P < 0.05), which showed that Bcl-2 acted as an anti-apoptotic protein in this epilepsy model." (PMID 33336032, 2020). "Previous studies demonstrated that caspase-3 was significantly activated in the brain of rats with epilepsy, cleaved caspase-3 significantly increased, the pro-apoptotic protein Bax increased, and the anti-apoptotic protein Bcl-2 decreased." (PMID 30983975, 2019). "In our study, bcl2 mRNA was decreased relative to bad expression after pilocarpine-induced epilepsy." (PMID 30159115, 2018). "This higher decrease in bcl2 : bad mRNA ratio suggests a more pronounced apoptotic cell death related with UCP2 silencing in the silent phase of the pilocarpine-induced epilepsy model." (PMID 30159115, 2018). "We found that knockdown of 11β-HSD1 reduced neuronal injury in hippocampal CA1 and DG areas induced by PTZ kindling, preventing the increased expression of pro-apoptosis proteins Bax and cleaved caspase-3 and the reduced expression of anti-apoptosis protein Bcl-2 in PTZ kindled epilepsy mice." (PMID 36064418, 2022). "Based on previous studies, Bad (Bcl2-associated agonist of cell death), an essential component of mitochondrial-dependent apoptosis, which increased sixfold in the PTZ group, has been reported in epilepsy by regulating cell death." (PMID 35345815, 2022). "However, compared with the epilepsy group, the expression level of Bcl-2 protein was significantly increased in both sodium valproate and GAA groups (p < 0.05, respectively)." (PMID 36093409, 2022). "VDAC1 regulated the pro-apoptotic effects of Bax and Bcl-2 in epilepsy." (PMID 33336032, 2020). "In this part, we could see that Bcl-2 inhibited the cell apoptosis, release of cytochrome C, and activation of caspase 9 in epilepsy, which could be strengthened by VDAC1 downregulation." (PMID 33336032, 2020). "The regulation of BCL2 may be a new pharmacological target for therapy-resistant epilepsy." (PMID 39767775, 2024).
epilepsy (continued). "In addition, overexpression of BDNF in cortical neurons from Sip1 mice resulted in increased expression of Bcl-2, Socs3 and Stat3 genes, which may contribute to the protection of neurons from injury in epilepsy." (PMID 39408863, 2024). "In the context of epilepsy progression, our research concentrated on how EGCG affects the balance between the anti‐apoptotic protein BCL2 and the pro‐apoptotic protein BAX." (PMID 41523603, 2025). "These discoveries about the functions of Bax, Bcl-2, NT4, BDNF, TLR4, NF-κB, and VEGF in epilepsy highlight how critical it is to focus on these pathways to create successful treatment plans." (PMID 40540445, 2025). "These discoveries about the functions of Bax, Bcl-2, NT4, BDNF, TLR4, NF-κB, and VEGF in epilepsy highlight how critical it is to focus on these pathways in order to create successful treatment plans." (PMID 40540445, 2025). "In summary, BAO mitigates KA-induced epilepsy-like behaviors by modulating the Bcl2/Bax/caspase-3 signaling pathway and the Notch1/GABA/GAD/GIRK signaling pathway, thereby playing a therapeutic role in epilepsy." (PMID 41011202, 2025). "During epilepsy progression, SNHG1 delays epilepsy progression by regulating the miR-181a/BCL-2 axis in vitro." (PMID 37684619, 2023). "GAA treatment significantly reduced the cortical neuron apoptosis of epilepsy and the expression of calcium-sensing receptor, p-P38, p-JNK, cleaved caspase-3, and Bax but increased the expression of both p-ERK and Bcl-2." (PMID 36093409, 2022). "Notably, our study is the first to demonstrate EGCG’s ability to restore the normal balance between BCL2 and BAX in the context of epilepsy, paving the way for further research into its potential as a treatment option for managing this challenging condition." (PMID 41523603, 2025). "Therefore, we propose evaluating the effects of RJ on the expression levels of Bcl-2 and/or Bax in hippocampal neurons in the OVX rat epilepsy model." (PMID 40292265, 2025). "Immunostaining detected Bcl-2 in 14 of 29 (48.3%) TBI patients with 2.9-fold increase when compared to epilepsy controls, but this was not statistically significant." (PMID 32570722, 2020). "Preclinical studies have shown that pathways such as the Bcl-2, IL-1β, NT-3 and the MAPK pathway that are also involved in miRNA dysregulation may also be promising new horizons for diagnosis and treatment of experimental as well as clinical epilepsy." (PMID 26528124, 2015).
esophageal squamous cell carcinoma (28 papers, 2013 to 2025). Esophageal squamous cell carcinoma (ESCC) is a type of esophageal carcinoma (EC) that can affect any part of the esophagus, but is usually located in the upper or middle third. "LncRNA PART1 in esophageal squamous cell carcinoma cell-derived EVs competitively combines with miR-129 to raise the expression of Bcl-2 in esophageal squamous cell carcinoma cells, thus inducing the drug resistance of tumor cells to gefitinib." (PMID 36405712, 2022). "Elevated PART1 is found in esophageal squamous cell carcinoma and promotes gefitinib resistance by competitively binding to miR-129 to facilitate Bcl-2 expression." (PMID 31367490, 2019). "Six1 also induces radioresistance via AKT/Bcl-2 pathway in esophageal squamous cell carcinoma and Bcl-2 is an inhibitor of mitochondrial apoptosis." (PMID 29113360, 2017). "Метформин индуцирует апоптоз и аутофагию в клетках ESCC (Esophageal squamous cell carcinoma) путем инактивации STAT3 и сдерживания экспрессии Bcl-2, а также индуцирует апоптотические пути в клетках рака надпочечников и поджелудочной железы путем активации каспазы-3." (PMID 36337018, 2022). "In addition, treatment of esophageal squamous cell carcinoma with metformin was shown to downregulate Bcl-2 expression through STAT3 inactivation in a previous study." (PMID 33652909, 2021). "Furthermore, the BAX/BCL2 ratio was shown to predict response to neoadjuvant radiochemotherapy in patients with advanced squamous-cell esophageal cancer." (PMID 23777485, 2013). "Here we have identified the major vault protein (MVP) and the B-cell lymphoma-2 (BCL2) gene as two potential factors driving MDR in esophageal squamous cell carcinoma (ESCC)." (PMID 35346194, 2022). "Several SNPs have been identified in the noncoding regions of BCL2 including rs1564483 (G>A) a functional variant in the BCL2 3′ UTR that is associated with decreased risk for non‐small‐cell lung cancer (NSCLC) while yet another variant rs2279115 (C>A) appears to increase risk of esophageal SCC." (PMID 30536617, 2019). "Phospholipase C epsilon 1 (PLCE1), has been found to promote angiogenesis and proliferation in esophageal squamous cell carcinoma by activating the NF-κB signaling pathway and inducing VEGF-C/Bcl-2 expression." (PMID 34193202, 2021). "In esophageal squamous cell carcinoma (ESCC), elevated levels of exosomal lncRNA prostate androgen-regulated transcript 1 (PART1) caused resistance to gefitinib by binding to miR-129 and increasing the expression of Bcl-2." (PMID 31467934, 2019). "In esophageal squamous cell carcinoma (ESCC), the lncRNA PART1 was enriched in exosomes and it acted as a ceRNA of miR-129 to upregulate Bcl-2 and promote gefitinib resistance." (PMID 39403602, 2024). "Metformin induced esophageal squamous cell carcinoma (ESCC) cell autophagy and cell death via inhibiting the STAT3-B-cell lymphoma 2 (BCL2) pathway and inhibited migration and invasion of ESCC cells by affecting NFκB nuclear localization." (PMID 33182253, 2020).
oral squamous cell carcinoma (28 papers, 2010 to 2025). "For instance, in oral squamous cell carcinomas, tumoregenesis was correlated to the overexpression of BCL-2 and PTEN loss of function." (PMID 30858525, 2019). "The aim of the study was to evaluate Bcl-2 expression in oral squamous cell carcinoma and dysplastic lesions of the oral cavity and to compare its expression with various grades of dysplasia and carcinoma." (PMID 39252711, 2024). "In poorly differentiated oral squamous cell carcinoma, Bcl-2 positivity was grade 1 in 33.3% and grade 2 in 66.7% of cases." (PMID 39252711, 2024). "In well-differentiated oral squamous cell carcinoma, Bcl-2 positivity was grade 0 in 66.7% of cases and grade 1 in 33.3% of cases." (PMID 39252711, 2024). "In moderately differentiated oral squamous cell carcinoma, Bcl-2 positivity was grade 1 in 63.6% of cases and grade 2 in 36.4% of cases." (PMID 39252711, 2024). "Recently, Li and colleagues described the in vivo effects of vicenin-2 (1; 30 mg kg−1), namely, the inhibition of Bcl-2 by triggering and/or activating apoptotic Bax in oral squamous cell carcinoma (OSCC) cell models." (PMID 36836763, 2023). "Decreased expression of antiapoptotic Bcl-2 protein was observed in human oral squamous cell carcinoma after berberine treatment." (PMID 23213296, 2012). "Thus, the histological grading of oral squamous cell carcinoma and the degree of oral epithelial dysplasia can be predicted and prognostically assessed using Bcl-2." (PMID 39252711, 2024). "Bcl-2 expression was higher in severe dysplasia compared to moderate dysplasia, which may indicate aggressive behaviour of tumour in poorly differentiated oral squamous cell carcinoma and severe dysplasia." (PMID 39252711, 2024). "Although research efforts on the capture and extraction of live cells in stomatology do not exist at present, live cell monitoring methods can be applied for specific markers in oral squamous cell carcinoma cells (BCL-2) for the rapid detection of oral diseases in the future." (PMID 33532080, 2021). "Future studies should investigate whether targeting the inhibition of PI3K and Bcl-2 may be more effective in treating patients with oral squamous cell carcinoma, which would improve the outcome of these highly resistant tumors." (PMID 31759362, 2019). "PAX9 is one of the nine members of "paired box” (PAX)-containing transcription factor family and its inhibition has been shown to induce apoptosis with increased cleavage of caspase-3 and PARP, increased expression of BAX and decreased expression of BCL-2 in oral squamous cell carcinoma." (PMID 28572861, 2017). "The aim of this study was to evaluate and compare the expression of bax and bcl-2 in oral lichen planus (OLP), well differentiated oral squamous cell carcinoma (WOSCC) and normal mucosa." (PMID 24551804, 2013). "Moreover, curcumin mediated inhibition of Notch1 activation also led to the downregulation of NF-κB and its target genes, including Bcl-2, cyclin D1, vascular endothelial growth factor (VEGF), and matrix metalloproteinase-9 (MMP-9) in oral squamous cell carcinoma cells." (PMID 24024180, 2013).
oral squamous cell carcinoma (continued). "Therefore, according to the effects of fucoidan in the up-regulation of Bax, cleaved caspase-3, and cleaved PARP, down-regulation of Bcl-2 and alteration of ΔΨm, it could be implied that fucoidan has potential in apoptotic induction via an intrinsic pathway on HSC-3 oral squamous cell carcinoma." (PMID 32856880, 2020).
renal cell carcinoma (27 papers, 2004 to 2025). "RU486 enhanced TRAIL-mediated apoptosis through the downregulation of Bcl-2 and cFLIP in human renal cell carcinoma Caki cells." (PMID 38535120, 2024). "Anisomycin in renal cell carcinoma cells can mediate Bcl-2/c-FLIP(L)/Mcl-1/death receptor 4 (DR4) to promote cell apoptosis and exert anti-tumor effects." (PMID 34164339, 2021). "Our results showed that knockdown of PDIA6 decreased Bcl-2 expression, increased Bax, and cleaved caspase-3 to reduce imatinib-resistance of renal cell carcinoma cells." (PMID 34781823, 2021). "Renal cell carcinoma expresses high levels of Bcl-2, which is one of the early discovered and thoroughly studied inhibitors of apoptosis." (PMID 18283311, 2008). "Taken together, these results suggest that Fas-dependent pathways as well as alternative pathways, which can be inhibited by Bcl-2, exist in renal cell carcinoma." (PMID 15188008, 2004). "β2-M may accelerate human renal cell carcinoma cell growth via activation of PI3K/Akt and ERK, and induce phosphorylation of the Bcl-xL/Bcl-2-associated death promoter (Bad)." (PMID 25292288, 2014). "For instance, AIM2 was capable of inhibiting the proliferation, invasion and migration of renal cell carcinoma (RCC) cells by upregulating autophagy-related genes (Bcl-2, Beclin-1, LC3-II and ATG5)." (PMID 31492049, 2019). "In renal cell carcinoma, CCL2 secreted by M2 macrophages increases muscleblind like splicing regulator 2 (MBNL2) expression, which in turn stabilizes B-cell lymphoma 2 (Bcl-2) mRNA, leading to the inhibition of Beclin 1-dependent autophagy and endowing RCC cells with invasion properties." (PMID 39286635, 2024). "Secondly, cell proliferation of imatinib-resistant renal cell carcinoma cells was suppressed by PDIA6 silencing, and the apoptosis was promoted with reduced Bcl-2, enhanced Bax and cleaved caspase-3." (PMID 34781823, 2021). "It has been revealed that CD133, CD24, CD105, Snail, Nanog, Twist, OCT-3/4, CRT2, BCL-2,MDR1, KLF4 and so on are stemness markers in CSCs of renal cell carcinoma or other types of tumor." (PMID 28279221, 2017). "The β2-M antibody may induce the human renal cell carcinoma cells apoptosis by inhibiting the phosphorylation of Akt and ERK, and activating JNK, resulting in the phosphorylation of Bcl-2 and decreased phosphorylation of Bad, leading to apoptosis." (PMID 25292288, 2014). "Renal cell carcinoma expresses high levels of Bcl-2 expression without gene amplification by us." (PMID 18283311, 2008). "Immunohistochemistry indicated FLI-1(+), CD99(+), Vimentin(+), CyclinD1(+), WT-1(+), EMA(+), Bcl2(-), Ki-67(+) 60%, CD56(-), CK(-), CD34(-), Desmin(-), and SMA(-), which suggested that renal clear cell sarcoma may not rule out renal cell carcinoma." (PMID 33859949, 2021).